CDK4 (cyclin dependent kinase 4)
Diseases named in the same sentence as CDK4 in open-access papers (continued):
Sharing a sentence is not in itself a finding about the gene and the disease.
breast cancer (continued). "This study therefore evaluates the cost-effectiveness of CDK4/6 inhibitors combined with endocrine therapy in the first- versus second-line setting for HR+/HER2- advanced breast cancer, using data from the SONIA trial and focusing on the Chinese healthcare system." (PMID 41383485, 2025). "In addition, amplification events are more common with CDK4 than CDK6 in primary luminal breast cancers: about 6% of luminal tumors carry CDK4 amplification, whereas CDK6 amplification is undetectable." (PMID 41226361, 2025). "Furthermore, in a PDX model derived from an ER+/HER2− breast cancer patient who progressed after multiple prior lines of chemotherapy and ET (including CDK4/6i palbociclib plus letrozole), ISM5043 as monotherapy greatly inhibited tumor growth." (PMID 41357671, 2025). "However, the effect of adjuvant therapy with CDK4/6 inhibitors has been inconsistent in early-stage breast cancer." (PMID 40002156, 2025). "CDK4/6 inhibitors have transformed treatment for HR + HER2 − advanced breast cancer (aBC)." (PMID 41331382, 2025). "The addition of cyclin-dependent kinase 4 and 6 inhibitors (CDK4/6is) to ET has recently been associated with improved progression-free survival (PFS) and, in some cases, overall survival (OS) in patients with invasive ER+ breast cancer." (PMID 40244377, 2025). "The CAPItello-291 Phase III clinical trial reported that Capivasertib combined with fulvestrant significantly prolonged progression-free survival in HR-positive advanced breast cancer patients, some of whom had disease progression after CDK4/6 inhibitor treatment." (PMID 40303285, 2025). "The selective CDK4/6 inhibitors (CDK4/6is)–palbociclib, ribociclib, and abemaciclib– are potent agents that arrest cell-cycle progression and demonstrate clinical efficacy in HR+ breast cancer, particularly when combined with anti-estrogen therapy." (PMID 41496429, 2025). "Beyond breast cancer, CDK4/6 inhibition also suppresses non–small‐cell lung cancer and melanoma." (PMID 39968498, 2025). "Preclinical studies have demonstrated that atirmociclib provides more effective CDK4 suppression and stronger tumour growth inhibition in HR+/HER2− breast cancer while markedly reducing its impact on hematopoietic stem and progenitor cells compared to dual CDK4/6 inhibitors." (PMID 40563591, 2025). "We present two cases of ILD in breast cancer patients receiving CDK4/6i alongside radiotherapy." (PMID 41244784, 2025). "Continuous CDK4/6 inhibition results in a sustained inhibition of ER+ breast cancer cells in xenograft models, which may have clinical relevance." (PMID 40427107, 2025). "In August 2023, the patient began first-line systemic therapy for ER+/HER2-low advanced breast cancer, consisting of the CDK4/6 inhibitor dalpiciclib (125 mg orally once daily) combined with the aromatase inhibitor fulvestrant (500 mg intramuscularly every 4 weeks)." (PMID 41487578, 2025). "Similarly, the CAPItello-291 study reported doubled mPFS (7.2 vs. 3.6 months) for AKT inhibitor capivasertib plus fulvestrant in advanced HR+/HER2− breast cancer, with consistent benefits observed in CDK4/6 inhibitor-pretreated subgroups (5.5 vs. 2.6 months)." (PMID 40421216, 2025). "Furthermore, recent research has demonstrated that CXCR4 is critical for maintaining breast cancer stemness and plays a role in resistance to CDK4/6 inhibitors through the activation of the WNT5A/β-catenin signaling pathway." (PMID 40362664, 2025). "Currently, CFI-402257 is under clinical investigation in breast cancer, in combination with Fulvestrant, as part of a trial evaluating its efficacy in patients with advanced ER+/HER2− breast cancer who have previously received CDK4/6i and endocrine therapy (NCT05251714)." (PMID 40949156, 2025). "In early-stage HR+ breast cancer, CDK4/6 inhibitors are being investigated for their potential use." (PMID 39930131, 2025).
breast cancer (continued). "Some evidence suggests that CDK4/6 inhibition leads to an RB-dependent increase in reactive oxygen species (ROS) levels, resulting in the activation of autophagy and limitation of senescence in breast cancer cells." (PMID 39800748, 2025). "However, in Turkey, the frequency of ILD development related explicitly to CDK4/6 inhibitors used in breast cancer, the impact of different CDK4/6 inhibitor molecules, and additional risk factors contributing to this frequency have not yet been identified." (PMID 40142360, 2025). "Stromal senescence following treatment with the CDK4/6 inhibitor Palbociclib alters the lung metastatic niche and increases metastasis of drug-resistant mammary cancer cells, and tumor-secreted GRP78 has been found to promote the establishment of a pre-metastatic niche in the liver microenvironment." (PMID 40732251, 2025). "Taken together, these data provide evidence that G2/M blockade by clinical-grade AukB or PLK1 inhibitors may be a viable clinical strategy in ER+ breast cancer cells, including certain CDK4/6i-resistant cancers." (PMID 40764324, 2025). "CDK4/6is are the standard of care when used in combination with other agents in breast cancer, so a key challenge in melanoma is identifying molecularly defined subsets of melanoma that may similarly respond to appropriate combination therapies." (PMID 40282469, 2025). "The incorporation of CDK4/6i into treatment regimens for HR+/HER2- advanced breast cancer has significantly improved clinical outcomes, demonstrating benefits in progression-free survival (PFS), objective response rate (ORR), overall survival (OS), and quality of life." (PMID 41244784, 2025). "Our genome-wide CRISPR knockout screen during imlunestrant treatment showed that known vulnerabilities in HR+ breast cancer, such as genes related to the CDK4/6-RB1 axis and PI3Kinase signaling pathway, remain essential in the presence of imlunestrant treatment." (PMID 40327396, 2025). "The large-scale phase-III clinical trials conducted with the PALOMA, MONALEESA, MONARCH, and DAWNA series have confirmed that CDK4/6 inhibitors play a pivotal role in extending progression-free survival and overall survival in HR-positive breast cancer patients." (PMID 41346024, 2025). "Thus, the synergistic antiproliferative effect of the combined inhibition of CDK2 and CDK4/6 in breast cancer can overcome acquired resistance to CDK4/6 inhibitors by enhancing senescence." (PMID 40904502, 2025). "•Real world study of 864 advanced breast cancer patients receiving CDK4/6 inhibitors." (PMID 40424680, 2025). "It has been demonstrated that in HR+ breast cancer patients, the level of monocytic and polymorphonuclear myeloid-derived suppressor cells (MDSCs) in peripheral blood are reduced after treatment with different CDK4/6is." (PMID 41463246, 2025). "Importantly, analysis of breast cancer biopsies collected from human patients before and after treatment showed a CDK4/6i-induced increase in lysosomal mass." (PMID 39930269, 2025). "Therefore, the implication of the body composition of patients in response to endocrine plus CDK4/6i therapy in patients with luminal breast cancer should be investigated." (PMID 39686815, 2025). "Additionally, resistance to CDK4/6 inhibitors in breast cancer is acquired through CDK2-mediated phosphorylation of c-MYC, which enables cells to escape senescence." (PMID 40904502, 2025). "In estrogen receptor–positive breast cancer specifically, CDK4 has become a specific target; its activity is inhibited by palbociclib to suppress breast cancer growth both in vitro and in mouse models as well as among patients with breast cancer." (PMID 40996961, 2025).
breast cancer (continued). "Moreover, TRIB3, which is highly expressed in prostate cancer, can be targeted by Palbociclib, a CDK4/6 inhibitor approved for the treatment of breast cancer, augmenting the response of prostate cancer cells to ferroptosis inducers." (PMID 39941896, 2025). "In a prior study of a smaller cohort of early-stage ER+ breast cancer patient tumors, we revealed that cancer resistance to endocrine and CDK4/6 inhibition therapy involves cancer cells shifting from estrogen-mediated signaling to alternative growth signal-mediated proliferation." (PMID 40341770, 2025). "Preclinical studies have indicated that CDK4/6 inhibitors can sensitize breast cancer cells to radiotherapy, possibly by inhibition of DNA damage repair response, enhancement of apoptosis and blockage of cell cycle progression, and inhibition of intra-tumor cellular metabolism and angiogenesis." (PMID 40719174, 2025). "The results manifested that NSRP1 might be involved in the immunosuppressive microenvironment and this could partly explain the NSRP1-related CDK4/6i resistance in breast cancer cells." (PMID 39667501, 2025). "However, despite this success in the treatment of breast cancer, the efficacy of CDK4/6 inhibition is variable, with 10–20% of tumors primarily resistant and an additional 40% becoming resistant to these drugs within the first 2 years." (PMID 39903505, 2025). "Interestingly, our current study showed that NSRP1 downregulation not only inhibited cell proliferation of ER+ breast cancer cells but also conferred CDK4/6i resistance." (PMID 39667501, 2025). "Additionally, upregulation of the IL-6/STAT3 pathway has been detected in ER + breast cancer resistant to CDK4/6i palbociclib, which mediates the upregulation of EMT and BCSCs pathways." (PMID 40949156, 2025). "Nevertheless, the involvement of m6A modifications in resistance to CDK4/6 inhibitors in ER+ breast cancer remains unclear." (PMID 40303916, 2025). "When CDK4/6 is inhibited, it restricts tumor cells from entering the next stage of mitosis, increasing evidence suggests that dysregulation of long-chain non-coding RNA (lncRNAs) is closely related to the occurrence and progression of breast cancer." (PMID 40093330, 2025). "This study provides insights into the potential therapeutic impact of targeting FGF signaling in overcoming resistance to CDK4/6 inhibitors and ET in ER+ breast cancer, as further explored in the ongoing Phase 1 clinical trial of tasurgratinib in combination with endocrine therapies (NCT04572295)." (PMID 40227585, 2025). "The included RCTs examined CDK4/6 inhibitors with ET in HR + HER2− early breast cancer patients." (PMID 40717978, 2025). "Moreover, current research conclusions on the impact of BMI on the efficacy of CDK4/6 inhibitor therapy in HR-positive advanced breast cancer were inconsistent." (PMID 41346024, 2025). "These impressive results raise the question of whether CDK4/6 inhibitors should be widely used to reduce long-term recurrence in HR + early breast cancer patients." (PMID 40717978, 2025). "Secondly, in advanced setting, breast cancer may have accumulated more genomic alterations that render tumor cells more sensitive to CDK4/6 inhibition." (PMID 39800748, 2025). "The discovery of CDK4/6 inhibitors has improved the treatment options for ER+ breast cancer." (PMID 40736275, 2025). "In the near future, with the introduction of perioperative immunological treatments, novel CDK4-specific inhibitors, and more targeted endocrine therapies, a significant proportion of previously high-risk HR+/HER2- breast cancers will likely show a relatively favorable prognosis." (PMID 40557948, 2025).
breast cancer (continued). "Numerous molecular studies suggest that the CDK4 and 6 pathway may be hyperactivated in breast cancers with positive hormone receptors." (PMID 40075608, 2025). "The success of CDK4/6 inhibitors in the treatment of patients with breast cancer has sparked the creation of novel cell cycle inhibitors that target various stages of the cell cycle, resulting in the emergence of various types of inhibitors with diverse anti-tumorigenic mechanisms." (PMID 40166466, 2025). "Therefore, identifying prognostic factors for CDK4/6 inhibitor efficacy was critical to optimize individualized treatment strategies in HR-positive advanced breast cancer." (PMID 41346024, 2025). "Additionally, INX-315 is currently in phase I/II trials for patients with recurrent or advanced/metastatic cancers, including HR+/HER2− breast cancer that has progressed following CDK4/6i therapy (NCT05735080)." (PMID 40949156, 2025). "Apart from CDK4/6, CDK2 is also involved in cell cycle progression through the G1, S, and G2 phases, and aberrant CDK2 activation is associated with CDK4/6 inhibitors in HER2-responsive breast cancers." (PMID 41463161, 2025). "Abemaciclib is a potent antiproliferative agent against HR+/HER2− breast cancer cells by selectively inhibiting CDK4/6‐mediated phosphorylation of retinoblastoma protein (RB), halting the cell cycle progression from G1 phase to S phase, and suppressing tumor cell proliferation." (PMID 39968498, 2025). "Palbociclib, a CDK4/6 inhibitor, plays a crucial role in the treatment of HR+ breast cancer." (PMID 39910045, 2025). "Additionally, AZD1775 has demonstrated potential to overcome resistance to breast cancer therapies such as trastuzumab and CDK4/6i, making it an attractive candidate among small-molecule drugs." (PMID 40949156, 2025). "Additionally, cell cycle inhibition is crucial in breast cancer therapy, as evidenced by the success of CDK4/6 inhibitors like palbociclib, ribociclib, and abemaciclib." (PMID 40430573, 2025). "The CDK4/6 specific inhibitors palbociclib (breast cancer phase III trial NCT01942135), ribociclib (melanoma phase II trial NCT01719380), and abemaciclib (breast cancer phase Ib trial NCT02057133) all potently inhibit CDK4/6 and are potentially useful in acute leukemias with CDKN2A/B alterations." (PMID 40247105, 2025). "Consistent benefit with capivasertib–fulvestrant compared with placebo–fulvestrant was observed in clinically relevant subgroups, including in patients with visceral metastases and in those who received prior CDK4/6 inhibitor treatment or prior chemotherapy for advanced breast cancer." (PMID 40346047, 2025). "Concomitant use of renin-angiotensin system inhibitors and cyclin-dependent kinase 4/6 inhibitors may have beneficial oncological effects in patients with breast cancer beyond their cardiovascular indications." (PMID 41417371, 2025). "Likewise, in another phase I/II trial (NCT04553133), the novel CDK2i PF-07104091 showed clinical efficacy in a previously largely treated advanced/relapsed breast cancer population progressing during ET plus CDK4/6is." (PMID 40244377, 2025). "CDK4/6 inhibitors revolutionized the treatment of HR-positive HER2-negative advanced breast cancer." (PMID 39860516, 2025). "It correctly inferred that palbociclib targets CDK4 in breast cancer with high confidence." (PMID 40293950, 2025). "In vivo, RGT-419B sustains tumor growth inhibition (TGI) more effectively than abemaciclib in heterotransplanted ER + breast cancer models, underscoring its potential as a novel therapeutic option for patients with CDK4/6i-resistant or refractory ER + breast cancer." (PMID 40949156, 2025). "Inhibition of CDK4/6 has marked a significant milestone in breast cancer treatment." (PMID 40142360, 2025). "It suggests that ISM5043 may be developed as a promising therapeutic option for ER+/HER2− breast cancer patients who experienced disease progression following CDK4/6i‐based therapy." (PMID 41357671, 2025).
breast cancer (continued). "The optimal second-line therapy in patients with ER+/HER2- metastatic breast cancer after progression on CDK4/6i and aromatase inhibitors remains unclear." (PMID 40427107, 2025). "Additionally, alterations in all three RAS family members—including KRASG12D, HRASK117R, and NRAS amplification—were found in HR+/HER2− breast cancers with poor responses to CDK4/6is." (PMID 40244377, 2025). "However, in contrast to vascular SMCs, miR-193a exhibits anti-proliferative actions in breast cancers cells and also inhibits CDK4 and Cyclin D1, while these proteins were upregulated in our study." (PMID 40801565, 2025). "Indeed, BRAF inhibitors in colorectal cancer, CDK4/6 inhibitors in breast cancer, and MEK inhibitors in melanoma all initially failed as single agents but are currently used in upfront combinations in their respective disease settings." (PMID 40581663, 2025). "This suggests that MDM2 inhibitors may be a crucial strategy to overcome resistance to endocrine therapy and CDK4/6i in ER + breast cancer." (PMID 40949156, 2025). "However, patients with breast cancer receiving oral cyclin-dependent kinase 4/6 inhibitor therapy still require regular hospital visits to monitor side effects." (PMID 40315425, 2025). "The expanding role of CDK4/6 inhibitors in breast cancer therapy underscores their importance in both metastatic and early-stage disease, with ongoing research focused on refining their application across breast cancer subtypes." (PMID 39930131, 2025). "Moreover, gene alterations in FGF/FGF receptor (FGFR) have been reported after treatment with a CDK4/6 inhibitor and ET in patients with ER+ breast cancer, suggesting that FGF signaling mediates resistance to these therapies." (PMID 40227585, 2025). "The postMONARCH trial is a global, phase 3, randomized, placebo-controlled study designed to evaluate the efficacy of abemaciclib plus fulvestrant in patients with HR+, HER2− advanced breast cancer and disease progression on prior CDK4/6 inhibitor plus endocrine therapy (NCT05169567)." (PMID 40141282, 2025). "Further study demonstrated that targeting the Akt/mTOR pathway could control the protein expressions of cyclin D1 and CDK4, thus contribute to the development of drug resistance in breast cancer." (PMID 41460862, 2025). "Although our laboratory data were collected from patients with metastatic breast cancer, there is no a priori reason to think that the results would be different for patients treated with CDK4/6is for breast cancer in the adjuvant setting or even for patients treated for other malignancies." (PMID 40361493, 2025). "In BRCA1-deficient murine breast cancer models, this phenotypic reprogramming was mediated by the activation of the stimulator of interferon genes (STING) pathway, which is an established driver of enhanced anti-tumour immune responses upon CDK4/6 inhibition." (PMID 41388212, 2025). "Endocrine therapy, often an aromatase inhibitor (AI), in combination with a cyclin-dependent kinase 4/6 (CDK4/6) inhibitor is the recommended first-line treatment option for certain patients with HR-positive/HER2-negative advanced breast cancer both internationally and in Japan." (PMID 39379782, 2025). "In hormone-driven breast cancer, CDK4 and CDK6 are often overactive." (PMID 41410553, 2025). "The phase II ELAINE-1 trial was conducted in HR+/HER2− relapsed breast cancer, with 40% of the subjects having the Y537S ESR1 mutation and progressing on prior AI and CDK4/6is; lasofoxifene was given as a single agent against fulvestrant and did not significantly prolong PFS." (PMID 40244377, 2025). "Data from DepMap, where ER+ breast cancer cell lines underwent systematic gene silencing to identify genes essential for survival, show that CDK4 knockout yields much lower DepMap CRISPR CERES scores than CDK6 knockout, indicating stronger dependency on CDK4 than CDK6 for viability." (PMID 41226361, 2025).